WWOX (WW domain containing oxidoreductase)
Diseases named in the same sentence as WWOX in open-access papers (continued):
Sharing a sentence is not in itself a finding about the gene and the disease.
cancer (continued). "We have previously shown that, in the neuT transgenic mouse model, C1qA induces the activation of the tumor suppressor WWOX, which downregulates Her2 expression, thus limiting cancer growth." (PMID 35203439, 2022). "In some cases, inhibition of autophagy by MIR375 and WWOX (WW domain containing oxidoreductase) can promote chemosensitivity of cancer cells." (PMID 35317831, 2022). "The WW domain-containing oxidoreductase (WWOX) gene is located at 16q23.1-q23.2 and spans the most active common fragile sites involved in cancer, FRA16D." (PMID 35328751, 2022). "Agonist Zfra4-10 or WWOX7-21 peptide, HYAL-2 antibody or sonicated hyaluronan HAson8, also activate the HYAL-2/WWOX/SMAD4 signaling for spleen Z cell activation in order to kill cancer cells in vitro and in vivo." (PMID 35883580, 2022). "WWOX and AP-2α demonstrated similar anti-cancer functionality in most biological processes with subtle differences in MMP-2/9 regulation; this contradicted that of AP-2γ, whose actions potentiated cancer progression." (PMID 34204827, 2021). "The research into the presence of this phosphorylated form of WWOX in cancer cells, and the determination of the molecular mechanisms responsible of this phosphorylation, also need to be performed." (PMID 33946771, 2021). "Such correlation was stronger with WWOX/HIF1A suggesting that WWOX modulates HIF1A function similarly to cancer cells." (PMID 33520443, 2021). "Another study suggested that TNK2 is an independent prognostic marker of HCC, which promotes cancer progression by downregulating WWOX and activating AKT signaling." (PMID 34421982, 2021). "In contrast, when Zfra4-10 and WWOX7-21 peptides are in combination in treating mice, binding of endogenous WWOX with protein partners is significantly reduced in many organs, and the cancer xenograft growth is increased." (PMID 34359949, 2021). "The inhibition of WWOX expression would therefore make cancer cells resistant to cell death, which is favorable to the development of cancer." (PMID 33946771, 2021). "WWOX gene is located on a common fragile site FRA16D on chromosome ch16q23.3-24.1, alterations of this gene is associated with cancer development." (PMID 34140629, 2021). "The inhibition of the expression of WWOX would increase their activity to an aberrant level, thus promoting the development of many types of cancer." (PMID 33946771, 2021). "Transiently overexpressed WWOX frequently sequesters transcription factors in the cytoplasm, and thereby blocks their transcription for prosurvival proteins in the nucleus of cancer cells in vitro." (PMID 34359949, 2021). "The localization of WWOX in a chromosomal region frequently altered in human cancers has initiated multiple current studies to establish its role in this disease." (PMID 33946771, 2021). "Metastatic cancer cells manipulate the expression of WWOX and TβRII to gain the advantage of survival." (PMID 34140629, 2021). "The find that cells expressing functional WWOX, repel cancer cells which express dysfunctional WWOX or lack this protein, in a manner mediated by WWOX epitope 286-299." (PMID 34140629, 2021).
cancer (continued). "We present evidence that introduction of WWOX expression in highly metastatic cancer cells affects several gene hubs and signaling pathways that are linked to migration, invasion and metastasis." (PMID 32300104, 2020). "Zfra-mediated cancer suppression is associated with downregulation of WWOX with S14 phosphorylation (p14-WWOX) in cancer cell-infiltrating organs." (PMID 32764489, 2020). "The gene interaction map of the SNPs that were found to interact with the Group 1 features reveals three individual cancer-related networks, among which the EGFR-BLK-ATR- and WWOX-linked networks are noticeable." (PMID 32632202, 2020). "The complex formation correlates with functional nullification between WWOX and Zfra in suppressing cancer growth." (PMID 32764489, 2020). "Reduction in WWOX phosphorylation at Ser14 in the cancer lesions correlates with cancer suppression." (PMID 32764489, 2020). "Activated Z cells relocate to the cancer lesions to cause cancer cell death, and this correlates with S14 de-phosphorylation of WWOX in the cancer lesions." (PMID 32764489, 2020). "This is supported by experimental data suggesting that reduced WWOX expression, a common occurrence in cancers, dysregulates dsDNA break repair, and enables resistance to dsDNA damaging agents." (PMID 33129329, 2020). "Hypothetically, Zfra4-10 binds to the membrane Hyal-2 of spleen Z cells and activates the Hyal-2/WWOX/SMAD4 signaling for cytotoxic Z cell activation to kill cancer cells." (PMID 32764489, 2020). "Given the prevalence of WWOX dysregulation in cancer and its multifaceted role in regulating cell cycle progression, cellular metabolism, and DNA damage repair responses, WWOX represents a potential target for therapeutic intervention." (PMID 33129329, 2020). "Proapoptotic tumor suppressor WW domain-containing oxidoreductase, designated WWOX, FOR or WOX1, is known to limit cancer growth and metastasis." (PMID 31123603, 2019). "This binding results in signaling together with WWOX and Smad4 to block cancer growth and inhibit the progression of neurodegeneration." (PMID 31752354, 2019). "In this study, we explored the functional significance of membrane bound WWOX and its binding partners in cancer suppression." (PMID 31752354, 2019). "Overexpressed WWOX exerts its proapoptotic pressure to cause skin BCC cells to secrete bFGF to support capillary microtubule formation, and this conceivably favors cancer cell growth and metastasis." (PMID 31123603, 2019). "We have recently demonstrated that when WWOX phosphorylation at Y33 is switched to S14, pS14-WWOX supports T cell differentiation, dramatically enhances cancer growth, and promotes the progression of neurodegeneration." (PMID 31752354, 2019). "Our experiment also revealed a correlation between the expression of WWOX and that of Bcl2, Ki67, and ErbB4 in this type of cancer." (PMID 31543760, 2019). "During the early stage of cancer progression, WWOX is Tyr33 phosphorylated (pY33-WWOX) and significantly upregulated, which restricts cancer initiation in vivo." (PMID 31123603, 2019).
cancer (continued). "In the very early stage of cancer initiation, WWOX is upregulated and then reduced, so as to facilitate cancer growth." (PMID 31123603, 2019). "In stark contrast, when S14 is phosphorylated, endogenous WWOX loses its proapoptotic function in blocking cancer growth and slowly enhancing neurodegeneration." (PMID 31752354, 2019). "Later, WWOX protein is reduced to enhance cancer cell growth, migration, invasiveness and metastasis." (PMID 31123603, 2019). "Despite its connection with cancer, WWOX indeed plays a critical role in neural development and neurodegeneration." (PMID 31315632, 2019). "In contrast, when pY33 is downregulated and pS14 upregulated in WWOX, pS14-WWOX supports cancer growth in vivo." (PMID 31752354, 2019). "WWOX7-21 and WWOX7-11 peptides probably drive the Hyal-2/WWOX/Smad4 signaling for cancer suppression by binding with membrane WWOX and/or Hyal-2." (PMID 31752354, 2019). "In contrast, WWOX blocked cancer cell-induced inflammation, so that the spleen size was the smallest." (PMID 31315632, 2019). "These peptides probably utilize the Hyal-2/WWOX/Smad4 signaling to exert cancer growth suppression and assist ceritinib-mediated enhancement of cancer cell death." (PMID 31752354, 2019). "Transiently overexpressed WWOX frequently sequesters transcription factors in the cytoplasm, and thereby blocks their transcription for prosurvival proteins in the nucleus in cancer cells in vitro." (PMID 30158849, 2018). "Together, WWOX phosphorylation at Ser14 supports the progression of neurodegeneration in the hippocampus and plaque formation in the cortex, as well as cancer progression." (PMID 30158849, 2018). "Since the in situ proximity ligation assay is well accepted to detect sub-cellular spatial molecular protein-protein interactions, this finding again verified the interaction of TMEM207 and WWOX in cancer cells." (PMID 30214895, 2018). "The connection between WWOX and cancer cell metabolism was established after linking WWOX protein to Hypoxia-inducible factor 1-alpha (HIF1α) function." (PMID 30619734, 2018). "Although the controversy about WWOX function, it will be exciting to try to test how would peptides that resemble WWOX WW domains affect cancer cell behavior to evaluate their therapeutic functions." (PMID 30619734, 2018). "The WW domain–containing oxidoreductase (WWOX) gene encompasses a common fragile sites (CFS) known as FRA16D, and is implicated in cancer." (PMID 30370248, 2018). "Considering the notion that WWOX is frequently lost in human cancers led to generation and characterization of mouse models that depict this ablation to further deepen our understanding of WWOX function in physiology and in pathophysiology." (PMID 30370248, 2018). "Apart from its role in cancer, many reports revealed direct involvement of WWOX in neurological as well as metabolic disorders." (PMID 30370248, 2018). "Second, the promoter region of WWOX can be hypermethylated, leading to gene silencing in several cancer cell types, i.e., Helicobacter pylori infection-related gastric cancer, intraductal papillary mucinous neoplasms of the pancreas." (PMID 30214895, 2018).
cancer (continued). "In the last few years, it has become evident that WWOX protein has pleiotropic functions, playing critical roles not only in cancer but also in other severe human pathologies including metabolic disorders and CNS-related syndromes." (PMID 30285739, 2018). "Peptides or monoclonal antibodies are being developed to target membrane Hyal-2 as well as WWOX and to activate Z cells in blocking cancer and neurodegeneration." (PMID 30158849, 2018). "Here, we examine the role of WWOX (WW domain containing oxidoreductase), a gene frequently lost in several cancers, in mediating paclitaxel response." (PMID 28749468, 2017). "Although we found that evodiamine increased the expression of WWOX, the role of WWOX in the anti-cancer activity of evodiamine was still obscure." (PMID 28708106, 2017). "High molecular weight HA increases the formation of endogenous Hyal-2/WWOX/Smad4 complex rapidly, followed by relocating to the nuclei in 20-40 min, in WWOX-expressing normal and cancer cells." (PMID 27845895, 2017). "Knockdown of WWOX in HepG2 and Hepa1-6 cells diminished the effects of evodiamine on the inhibitory effect of cancer cell growth, indicating that evodiamine induced anti-cancer activity through a WWOX-dependent pathway." (PMID 28708106, 2017). "Numerous studies have reported that WWOX alterations occur in many types of cancer cells and in situations of cellular stress." (PMID 29152092, 2017). "Recently, the CNV-67048 of WW domain-containing oxidoreductase (WWOX) was reported to alter cancer risks." (PMID 27190995, 2016). "The WWOX protein is a tumor suppressor that is lost or under-expressed in a wide variety of cancers, including breast, prostate, ovarian, and lung." (PMID 26675548, 2016). "WW domain containing oxidoreductase (WWOX) gene was cloned in 2000; alteration has been seen in many cancer cells." (PMID 27495153, 2016). "Regarding the three genes (WWOX, CADM1 and CCDC80) detected as SETDB2 target genes in our study, their loss or reduced expression has been reported in various cancers." (PMID 27572307, 2016). "In support of this assumption, germline mutations or loss of function of WWOX, RORA, and PARK2 are associated with neurological diseases, whereas somatic deletions are associated with cancer." (PMID 27977694, 2016). "And, this leads to a general belief that WWOX sequesters prosurvival transcription factors in the cytoplasm to block cancer growth." (PMID 27999774, 2016). "Future studies in this direction should further deepen our understanding of WWOX functions in the DDR related to cancer and likely other pathologies." (PMID 26675548, 2016). "Several studies have demonstrated that the WWOX gene is important in malignant tumors, particularly in the development of hormone-dependent tumors." (PMID 25891642, 2015). "Together these results represent a plausible mechanism for low WWOX levels contributing to poor prognosis in various cancers." (PMID 26302329, 2015). "Understanding the conserved cellular pathways to which WWOX contributes provides novel possibilities for the development of therapeutic approaches to restore WWOX function in cancer." (PMID 26302329, 2015). "For example, WW domain-containing oxidoreductase (WWOX), as a modulator of cancer metabolism, via its first WW domain, physically interacts with HIF1α and modulates its levels and transactivation function." (PMID 25685782, 2015). "Ectopic expression of WWOX in different cancer cell lines resulted in apoptosis in vitro and marked inhibition of tumorigenicity in vivo." (PMID 27551470, 2015). "A pro-apoptotic role for WWOX in vitro has previously been reported for many different cancer cell types; multiple myeloma, colon, gall bladder, cervical, leukaemic, glioblastoma, hepatoma, lung, pancreatic and squamous epithelia." (PMID 26302329, 2015).
cancer (continued). "While transiently overexpressed WWOX restricts relocation of transcription factors to the nucleus for suppressing cancer survival, physiological relevance of this regard in vivo has not been confirmed." (PMID 25537520, 2014). "WWOX, encoding WW domain-containing oxidoreductase, spans FRA16D, the second most common chromosomal fragile site frequently altered in cancers." (PMID 24456803, 2014). "Transiently overexpressed WWOX binds transcription factors AP-2, p73, and c-Jun and block their nuclear relocation in vitro, which suppresses cancer cell survival." (PMID 23459853, 2013). "We have shown the role of WWOX in controlling cell migration and metabolic alterations, and discussed the effects of WWOX deficiency and TMZ resistance in cancer cells." (PMID 23459853, 2013). "Despite the frequent suppression of WWOX, FHIT and p73 expression in numerous cancers, complete gene inactivation by the deletion of one allele and a second mutation or homozygous deletion is extremely rare." (PMID 24137446, 2013). "Overexpressed WWOX induces apoptosis and inhibits proliferation of human hepatic carcinoma cells and many cancer cell types." (PMID 23459853, 2013). "Nonetheless, expression of tumor suppressor WWOX is increased during the early stages of cancer initiation and growth, and is then dramatically reduced at the late stages of differentiation in skin cancer both in humans and mice." (PMID 27234387, 2013). "The WWOX tumor suppressor gene is inactivated in many types of human cancers by genomic rearrangements, aberrant mRNA splicing, homozygous deletions and epigenetic silencing." (PMID 19936220, 2009). "Allelic losses and rearrangements affecting the WWOX locus have been described in various human cancers." (PMID 19936220, 2009). "To investigate whether the impairment of WWOX promotes cancer progression, we first analyzed the expression of WWOX in 60 cancer types using the dataset of The Cancer Genome Atlas (TCGA)." (PMID 41124647, 2026). "WWOX and HIF1α proteins are involved in cancer progression; their functions are closely related." (PMID 41007296, 2025). "Single inhibitors of glycolysis often fail due to the metabolic flexibility of cancer cells; therefore, future therapies should target HIF1α (e.g., via WWOX), which may more effectively inhibit aberrant glycolysis." (PMID 41007296, 2025). "WWOX and HIF1α were studied separately and extensively in many cancers." (PMID 41007296, 2025). "In conclusion, the WWOX/HIF1A expression ratio might be considered as a potential biomarker determining the prognosis of cancer patients." (PMID 41007296, 2025). "Furthermore, aberrant splicing of the WWOX gene contributes to the production of abnormal transcripts found in various cancers." (PMID 41228229, 2025). "Research has indicated that exosomal miR-625-3p, secreted by cancer-associated fibroblasts, promotes the proliferation, invasion, and EMT of CRC cells, inhibits apoptosis, and enhances chemotherapy resistance by downregulating CELF2/WWOX." (PMID 41228229, 2025). "Nevertheless, these results may constitute a starting point for further studies on the significance of the WWOX/HIF1A ratio in various types of cancer." (PMID 41007296, 2025).